ENSG00000199894
Synonyms: LOC124900892
Gene: Small nucleolar RNA gene on chromosome 4 (110,433,109 to 110,433,188, reverse strand). Ensembl gene ENSG00000199894.
Gene Ontology:
Biological process: RNA processing
Cellular component: nucleolus
Homologues: Orthologues: rat LOC120100395 (80% identical), rat LOC120094475 (79% identical), mouse Gm24339 (75% identical).